CFTR (CF transmembrane conductance regulator)
Diseases named in the same sentence as CFTR in open-access papers (continued):
Sharing a sentence is not in itself a finding about the gene and the disease.
cancer (continued). "CF-related germline mutations are not the likely cause of reduced CFTR mRNA expression in these cancers as F508del, which represents ~ 70% of CF alleles, results in a 90% decrease in protein levels but a very modest or no reduction in mRNA." (PMID 32326161, 2020). "Overall, the potential impact of CFTR deficiency in CRC on oxidative stress may be context dependent, as may be true for cancers in general." (PMID 32326161, 2020). "Although many of these studies provide only circumstantial correlations between CF and cancer, it remains unclear whether carcinogenesis is a direct consequence of dysfunctional CFTR, and the compelling accumulated evidence calls for urgent investigation." (PMID 32365523, 2020). "This may be due to the fact that CF cells display a partial EMT/cancer-like phenotype and that CFTR has been proposed to act as a tumor suppressor." (PMID 32630830, 2020). "However, it should be noted that almost all of these studies focused on carcinoma, probably due to the fact that CFTR was thought to be exclusively expressed in epithelial cells." (PMID 32463592, 2020). "The seemingly contradictory findings indicate the role of CFTR in cancer development might be tissue specific." (PMID 27769067, 2016). "Therefore, it is clinically important to study CFTR in each cancer type to determine its prognostic potential." (PMID 27769067, 2016). "Whole-genome sequencing of Russians without CF and malignant neoplasms (n = 1825), as well as healthy Russians from the general population (n = 10,000), identified the carriage of pathogenic CFTR variants in 2.85% of the first group and 2.21% of the second group." (PMID 40724872, 2025). "CFTR may drive cancer via several different mechanisms including regulation of ion transport across cellular membranes, an increase in pro‐inflammatory cytokines and chemokines which can promote a pro‐tumorigenic environment, and involvement in proliferation and cell survival pathways." (PMID 41147257, 2025). "When considering all cancer types, pathogenic somatic variants in CDKN2A (identified in 12%.7 of CFTR PV carriers; Sidak‐corrected p = 0.0069) and CDKN2B (identified in 4.2% of CFTR PV carriers; Sidak p = 0.0428) were more common in our cohort of CFTR PV carriers than in the global COSMIC database." (PMID 41147257, 2025). "Additionally, CFTR may interact with other proteins involved in cell cycle regulation and apoptosis, influencing the behavior and survival of cancer cells." (PMID 37686519, 2023). "For example, CFTR dysfunction may disturb the balance of intracellular chloride and bicarbonate ions, affecting pH levels and influencing critical metabolic processes in cancer cells." (PMID 37686519, 2023). "Except for the variant c.1521_1523delCTT in CFTR that was found as single variant in a PanC with negative family history for cancer, all the other pathogenic-likely pathogenic variants identified in this study were in patients classified as unselected PanC accordingly to their family anamnesis." (PMID 36717774, 2023). "It should be noted that the potential effect of CFTR modulators in suppressing tumor aggressiveness is still a hypothesis and, thus, the outcome of these modulator drug treatments in cancer patients needs to be monitored for the development of future treatment regimens based on them." (PMID 35743652, 2022). "How these sometimes-contradictory stress responses and their connections to CFTR influence carcinogenesis remains unclear, and they may well be tissue and cancer context-dependent, and therefore the role of CFTR in these tissues and cancers may also be context-dependent." (PMID 35743652, 2022). "Another facet of “lineage ambiguity” was the strong expression of FOXI1 in tuft cell-like cancers of different histotypes because this is the master regulator of ionocytes, which regulate airway surface physiology by expressing characteristic functional molecules, such as CFTR in the lung." (PMID 36402755, 2022).
cancer (continued). "This has also led to the proposal that CFTR may function as a tumor suppressor gene with evidence accumulating that a low expression of CFTR stimulates the progression of different types of cancer." (PMID 34947992, 2021). "Mutations or absence of CFTR result in pathogeneses, including cancer." (PMID 32182826, 2020). "Altogether, these studies suggest that CFTR interactors/pathways may be tissue/cancer specific." (PMID 32365523, 2020). "While uPAR has been shown to be regulated by NFκB in various cancers, this study is the first to demonstrate the involvement of NFκB in the regulation of uPAR expression by CFTR in human endometrial cells since NFκB inhibitors can reverse the CFTR overexpression-induced upregulation of uPAR." (PMID 28978008, 2017). "Notably, CFTR may act as either a tumor suppressor or a context-dependent oncogene, depending on tissue type and signaling milieu, highlighting its complex role in cancer biology." (PMID 42274626, 2026). "These differential behaviours might also be partly explained by the induction of ER stress in p.Phe508del-CFTR expressing cells (Trouvé and Férec, 2025) as some studies suggest that chronic ER stress can drive abnormal proliferation, a phenomenon observed in cancer and stem cell systems." (PMID 40910003, 2025). "To assess the impact of CFTR inhibition on PDAC liver metastasis, we performed intrasplenic implantation of KPC-derived cancer cells followed by treatment with CFTRi or vehicle control for seven consecutive days." (PMID 38355776, 2024). "Assays can be broadly partitioned into those which detect either non-cancer-related variants (eg, CFTR p.F508del is universally accepted as pathogenic, but solely as a mutation that results in cystic fibrosis and has no known association with oncology) or cancer-related variants." (PMID 38982622, 2024). "Knockdown of CFTR in NSCLC cells increases the EMT phenotype, whereas CFTR overexpression suppresses cancer progression in vitro and in vivo." (PMID 37381723, 2023). "Differential gene expression analysis identified that inflammation‐responsive transcription factors, such as CCL3L1, characterized patients with relapse T‐ALL, along with deregulation of several key cancer regulators such as FAT3, CFTR and GLI3 (Figure SF1A)." (PMID 36819185, 2023). "It has been reported that most of the 8 ARGs (VIM, UFM1, TSC2, SRC, MEFV, CTTN, CFTR and CDKN1A) are related to cancer." (PMID 35121801, 2022). "Our previous studies have indicated that dysfunction of CFTR promotes EMT and cancer metastasis via both genetic and epigenetic pathways, such as uPA, NF-κB, MAPK and miR-193." (PMID 27769067, 2016). "The demographics of the total APG cohort and those with CFTR PVs were not significantly different with regard to sex, race, or age at diagnosis, but the distribution of cancer types was significantly different between the total APG cohort and those with CFTR PVs." (PMID 41147257, 2025). "CFTR has been shown to be involved in cellular proliferation pathways including epithelial–mesenchymal transition (EMT), which is a latent developmental process, that can be re‐activated in fibrosis and cancer." (PMID 41147257, 2025). "Approximately 5 years after the cancer diagnosis, with no signs of relapse, the patient was started on CFTR (Cystic fibrosis transmembrane conductance regulator) modulator treatment." (PMID 38105789, 2023).
cancer (continued). "An increasing number of emerging studies show that CFTR plays a role in fundamental cellular processes which include development, epithelial differentiation/polarization, regeneration, migration and proliferation as well as in EMT and cancer." (PMID 32365523, 2020). "We speculate that this may be due to the fact that CF cells display a partial EMT/cancer-like phenotype, which leads to altered signaling pathways, namely those linking KLF4 to CFTR." (PMID 32630830, 2020). "The authors show conservation of TAD organisation around the CFTR locus in five different cancer cell lines, two of which do not express the gene." (PMID 28615069, 2017). "CFTR (cystic fibrosis transmembrane conductance regulator) is involved in Wnt-dependent hematopoiesis, which interacts with adherens junction molecule AF-6/afadin via PDZBD (PDZ binding domain), thus regulating epithelial polarity and affecting cancer metastasis." (PMID 36142160, 2022). "However, to date there have been no reports yet linking CFTR dysregulation to aberrant Wnt/β-catenin signaling in these cancers." (PMID 35743652, 2022). "The multiple associations of CFTR and epithelial differentiation/EMT have been recently reviewed and reflect the idea that CF cells display a more cancer-like (vs. non-CF cells) phenotype due to the occurrence of a partial EMT, considered as a first stage into carcinogenesis." (PMID 32937756, 2020). "Moreover, CFTR localization to the intestinal crypt stem cell compartment permits it to influence stem cell function and therefore, ultimately, CRC development as the intestinal stem cell is the likely cancer progenitor cell." (PMID 32326161, 2020). "Furthermore, absence of functional CFTR has been linked to increased epithelial cell proliferation, induction of epithelial-mesenchymal transition (EMT) and higher incidence of various cancer forms in people with CF (pwCF) and even CF carriers." (PMID 40910003, 2025). "The incidence of many cancers increases with age, and without age-matched epidemiological comparisons to the general population, it is difficult to determine the extent to which the observed rise is attributable to CFTR modulators versus the natural aging process." (PMID 41154689, 2025). "Finally, we identified five key EMT pathways dysregulated in CF cells and several proteins among the F508del-CFTR–specific YAP1 interactors, which emerge as major hubs possibly mediating the crosstalk among these pathways and appearing as potential therapeutic targets for both CF and cancer." (PMID 35500936, 2022). "The direct implication of CFTR in cancer progression is still somewhat controversial since CFTR has not yet been connected in any direct signaling pathways, however, CFTR may act by regulating intracellular Cl− concentrations, and so influencing the intracellular environment." (PMID 30021582, 2018). "Altogether, these data indicate for the first time that absence of functional CFTR leads to (partial) EMT, that this process is mediated by TWIST1 and that functional CFTR confers some degree of EMT protection (e.g. to cancer)." (PMID 33106471, 2020). "CFTR, found in epithelial cells functions as a cAMP-activated ATP-gated anion channel and SLC6A14 functions as Na+ and Cl− dependent neutral and basic amino acid transporter, but their roles in cancer are not known." (PMID 25505737, 2014).
tumor (81 papers, 2010 to 2026). "A probable explanation for the role of CFTR as a tumor suppressor is its emerging association to epithelial–mesenchymal transition (EMT)." (PMID 35500936, 2022). "In many of these malignancies, loss of CFTR correlated with increased tumor stage and reduced disease-free or overall survival." (PMID 32326161, 2020). "CFTR is a tumor suppressor and downregulated expression of CFTR is linked to CRC not only in CF patients but in the general population." (PMID 33363037, 2020). "Of note, hypermethylation of CFTR or the F508del CFTR has been suggested as a tumour risk biomarker for young CF patients." (PMID 30764828, 2019). "CFTR inhibition caused significant reduction in metastatic tumor burden at advanced stage." (PMID 38355776, 2024). "The mechanisms underlying the action of CFTR as a tumor suppressor are not clearly understood." (PMID 37046605, 2023). "However, given that CFTR deficiency has been found in a variety of tumor types that occur independently of Wnt/β-catenin signaling, it is possible that the CFTR function as a tumor suppressor extends beyond the Wnt/catenin pathway." (PMID 37175647, 2023). "The mechanisms underlying the actions of CFTR as a tumor suppressor are not clearly understood." (PMID 36483264, 2022). "In addition, a high level miR-125b was associated with lymph node metastasis and poor tumor differentiation, and the inverse relationship between miR-125b and CFTR/CGN was observed in both primary CRC and distant metastasis tissues." (PMID 34830864, 2021). "Mechanisms underlying the actions of CFTR as a tumor suppressor are not clearly understood." (PMID 32326161, 2020). "Moreover, EMT induction by dysfunctional CFTR also provides a direct (causal) link to its role as tumour suppressor." (PMID 32365523, 2020). "Finally, identification of the spectrum of mutations found in CRC may aid in understanding which CFTR functions are important for tumor suppression." (PMID 36765944, 2023). "However, the possible underlying mechanisms for CFTR modulating tumor progression remain to be elucidated, which might eventually lead to the development of new anti-NPC strategies." (PMID 27769067, 2016). "Thus, CFTR may be associated with tumor drug resistance, modulating the efficacy of chemotherapy and then affecting patient metastasis rate after chemotherapy." (PMID 27769067, 2016). "These published studies, together with our results, should stimulate research efforts aimed to verify, in CFTR-overexpressing tumor cell lines, the interplay between pre-miR-145-5p treatment, CFTR downregulation, and effects on in vitro tumor phenotype." (PMID 37104011, 2023). "We found IC2 LoM as cause of BWSp, likely pathogenic CFTR variants as possible germline lesions predisposing to CRC, and a chromosomal and epigenome instability as an altered molecular profile of the tumor genome." (PMID 37046605, 2023). "Accordingly, knockdown and/or inhibition of CFTR suppresses the proliferation of tumor cells in vitro and in vivo." (PMID 37104011, 2023). "CFTR also acts as a tumor suppressor in diverse sporadic epithelial cancers in many tissues, primarily due to the silencing of CFTR expression via multiple mechanisms, but especially due to epigenetic regulation." (PMID 35743652, 2022). "Several lines of evidence have indicated that CFTR acts as a tumor suppressor in multiple disease scenarios due to its anion channel function." (PMID 34830864, 2021). "In particular, the silencing of CFTR by promoter hypermethylation in a majority of tumor types enhanced the reliability of our bioinformatics-based analysis." (PMID 31894857, 2020). "It is also possible that the two mechanisms occur in parallel, rendering CFTR a pleiotropic tumour suppressor." (PMID 32365523, 2020). "Overexpression of CFTR suppresses CRC tumor growth by inhibiting the proliferation, migration, and invasion of CRC cells." (PMID 33363037, 2020).
tumor (continued). "CFTR expression was also significantly increased in ovarian cancer where it correlated positively with the tumour progression state and malignancy degree (cell invasion, motility and proliferation)." (PMID 32365523, 2020). "For instance, studies from both other groups and ours have revealed that CFTR suppresses tumour progression via PDZ domain‐dependent protein‐protein interaction." (PMID 32463592, 2020). "A study of 90 Stage II CRC patients stratified by tumor CFTR expression showed disease-free survival at 3 years in the 25% of patients with lowest CFTR expression was 30% lower than those with higher expression." (PMID 33363037, 2020). "Because of the emerging roles of CFTR as a tumour suppressor and as a key player in development and epithelial differentiation, it is plausible to envisage its involvement in EMT." (PMID 32365523, 2020). "Our Western blot results also showed that the expression of Bcl2 was significantly up‐regulated in CFTR‐overexpressing U87‐inoculated tumours compared to the tumours injected with control U87 cells." (PMID 32463592, 2020). "CFTR is an indispensable ion channel for epithelial function and was recently discovered to participate in tumor progression or suppression depending on the type of tumor." (PMID 32182826, 2020). "In the subcutaneous model, the tumour size was about 3 times and the tumour weight was more than 2 times in CFTR‐overexpressing tumours than control tumours." (PMID 32463592, 2020). "Subsequent detailed examination of tumour samples revealed that the mRNA expression level of Bcl2 was significantly up‐regulated in CFTR‐overexpressing tumours." (PMID 32463592, 2020). "In this study, we demonstrated tumor suppressor activity of CFTR in HNC and found several candidate genes potentially regulated by CFTR." (PMID 32182826, 2020). "Consistently, in orthotopic model, the tumour size was significantly increased in CFTR‐overexpressing tumours compared to control cell‐inoculated tumours as well." (PMID 32463592, 2020). "The authors observed that the specific knockout of CFTR expression in the mouse gut leads to a significantly increased incidence of tumour development in the colon and in the entire small intestine." (PMID 30764828, 2019). "It has been reported that MARCH2 mediates polyubiquitination and degradation of CFTR, leading to attenuation of CFTR-mediated autophagy in tumor cells." (PMID 31404274, 2019). "Our previous studies have demonstrated that cystic fibrosis transmembrane conductance regulator (CFTR) acts as a tumor suppressor regulating cell migration." (PMID 28978008, 2017). "Since metastasis is the main cause of tumor relapse and high mortality of NPC, we also evaluated the prognostic potential of CFTR using clinical outcomes." (PMID 27769067, 2016). "Since metastasis is the main cause of tumor relapse and high mortality of NPC, we also evaluated the prognostic potential of CFTR using clinical outcomes collected by the follow-up study." (PMID 27769067, 2016). "In one of the NPC sections containing both tumor tissue and adjacent normal tissue, we observed a transitional expression pattern of CFTR with strong expression in the normal nasopharyngeal tissue but much decreased expression in tumor region." (PMID 27769067, 2016). "The previous studies have shown that TNFα down-regulated CFTR mRNA expression in HT-29 cells, a colon epithelium-derived tumor cell line, in a dose- and time-dependent fashion." (PMID 23626828, 2013). "Moreover, the CFTR (cystic fibrosis conductance regulator protein) channel facilitates the entry of chloride ions, is considered a tumor suppressor, and is involved in the proper epithelial differentiation." (PMID 37408210, 2023).